SNRPD1 (small nuclear ribonucleoprotein D1 polypeptide)
Diseases named in the same sentence as SNRPD1 in open-access papers:
SNRPD1 is named in the same sentence as 32 diseases in open-access papers, as found by Europe PMC text mining. Sharing a sentence is not in itself a finding about the gene and the disease. The quoted sentences say what the papers report.
breast carcinoma (11 papers, 2016 to 2024). "We, in addition, identified one trans-eQTL (rs6733100) of SNRPD1 independently prognostic of breast cancer survival, with the rare allele conferring a protective effect." (PMID 37098488, 2023). "Given the positive association between SNRPD1 over-expression and poor breast cancer survival, we investigated the expression quantitative trait loci (eQTL) of SNRPD1 using data retrieved from TCGA." (PMID 37098488, 2023). "High SNRPD1 gene expression was significantly associated with increased hazard on breast cancer specific and distant metastasis (GSE24450) or relapse free survival (GSE1456, GSE4922) in three independent patient series (p<0.0001, HR=1.89 from meta-analysis)." (PMID 37098488, 2023). "We therefore decided to focus on SNRPD1 and explore its potential diagnostic and therapeutic values in breast cancers." (PMID 33879154, 2021). "We identified the novel association of SNRPD1 with cell cycle progression in breast cancers, and therefore proposed SNRPD1 as a novel target for breast cancer control through halting cell cycle progression at the G0/G1 phase." (PMID 33879154, 2021). "A recent reprint identified SNRPD1 as one of the top 10 essential ribosome binding proteins for breast cancer survival from both the genome-scale RNAi loss-of-function screens (DEMETER2) and the genome-scale CRISPR-Cas9 loss-of-function screens (CERES)." (PMID 33879154, 2021). "And silencing SNRPD1 in breast cancer cells may cause tumor cell growth to stop and cell cycle arrest in the G0/G1 stage 40." (PMID 34976182, 2022). "Our study revealed that SNRPD1 over-expression was significantly associated with genes involved in cell cycle, cell mitosis and chromatin replication, and silencing SNRPD1 in breast cancer cells could lead to halted tumor cell growth and cell cycle arrest at the G0/G1 stage." (PMID 33879154, 2021). "SNRPD1 is involved in pre-mRNA splicing and reportedly upregulated in several cancers, including lung adenocarcinoma and breast cancer." (PMID 38157275, 2024). "We next examined the sensitivity of TNBCs in response to doxorubicin, a common form of adjuvant chemotherapy for breast cancer treatment especially among TNBCs, after silencing SNRPD1 or SNRPE using MDAMB231 and HCC1937 as the cell models." (PMID 37098488, 2023). "The SNRPD1 expression quantitative trait loci, rs6733100, was foundindependently prognostic of breast cancer survival using TCGA data." (PMID 37098488, 2023). "One eQTL of SNRPD1, rs6733100, was found independently prognostic of breast cancer patient survival." (PMID 37098488, 2023). "Given the differential associations of SNRPD1 and SNRPE on breast cancer survival, we explored their functionalities on cancer cell growth using in vitro assays." (PMID 37098488, 2023). "Silencing eitherSNRPD1 or SNRPE independently suppressed the growth of breast cancer cells, butdecreased migration was only observed in SNRPD1-silenced cells." (PMID 37098488, 2023). "We showed, in this study, that SNRPD1 over-expression was prognostic of poor breast cancer survival, promoted cancer cell proliferation and migration due to, possibly, reduced cell cycle S phase and enhanced genome stability." (PMID 37098488, 2023). "Studies have shown that SNRPD1 overexpression promotes the development of breast cancer by cooperating with genes involved in the cell cycle, mitosis, and chromatin replication." (PMID 34976182, 2022). "We are the first to link the role of SNRPD1 with cell cycle progression and explain the distinct clinical outcomes of breast cancer subtypes using its differential expression." (PMID 33879154, 2021). "SiRNA-mediated depletion of SNRPD1 leads to a significant reduction in cell viability in breast cancer, lung cancer, and leads to autophagy by mTOR pathway." (PMID 34130650, 2021). "As a result, no visible variation on SNRPE expression was found by silencing SNRPD1, suggestive of the independent role of SNRPD1 in breast cancer survival." (PMID 33879154, 2021).
breast carcinoma (continued). "SNRPE and SNRPD1, core components of the spliceosome, can promote viability of lung cancer, breast cancer and melanoma." (PMID 32939931, 2020). "We warranted the combined use of drugs targeting SNRPD1 and anthracycline type of chemotherapies in breast cancer management that may generate undesirable therapeutic outcome as targeting SNRPD1 triggered the resistance of TNBC cells to doxorubicin." (PMID 37098488, 2023). "SNRPD1 up-regulation contributed to breast cancer cell proliferation." (PMID 35356432, 2022). "In addition, SNRPD1/3 plays a regulatory role in breast cancer through cell cycle regulation, and SRSF3/7 is an RNA-binding protein associated with metastasis and recurrence." (PMID 36434140, 2022). "Our results suggested the prognostic value of SNRPD1 on breast cancer survival, its potential as the therapeutic target halting cell cycle progression for breast cancer control, and warranted special attention on the combined use of doxorubicin and drugs targeting SNRPD1." (PMID 33879154, 2021). "In addition, spliceosome assembly components were revealed as the most enriched pathway deregulated in breast cancers with SNRPD1 being an important player according to exonic expression profiling of 120 breast tumors and 45 benign lesions." (PMID 33879154, 2021). "This study implicates the therapeutic potential of SNRPD1 in breast cancer control that might be expanded to other types of cancers and warrants the combined use of doxorubicin and drugs targeting SNRPD1 in treating triple negative breast cancers, which are subjected to experimental validations." (PMID 33879154, 2021). "We also differentiated SNRPD1 and SNRPE regarding their roles on breast cancer progression and onco-therapeutic implications." (PMID 37098488, 2023). "While some of these spliceosome genes, such as SNRPA1, SNRPD1, USP39, HNRNPU, and HNRNPC, have been shown to play an important role in promoting TNBC cell survival, proliferation, and response to chemotherapy, others are yet to be studied in breast cancer." (PMID 39418101, 2024). "Specifically, SNRPD1 over-expression is prognostic of poor breast cancer survival whereas SNRPE is not." (PMID 37098488, 2023). "However, we observed different effects of SNRPD1 and SNRPE on breast cancer cells that motivated us to investigate their differential roles and mechanisms associated with carcinogenesis." (PMID 37098488, 2023). "SNRPD1 and SNRPE, among other Sm proteins, were shown overexpressed in a subset of highly aggressive breast cancers, and were proposed as novel onco-therapeutic targets since the depletion of either one halted breast cancer growth without affecting the quasi-normal MCF10A cells." (PMID 37098488, 2023). "We showedthat high SNRPD1 gene expression was prognostic of poor breast cancer survival whereasSNRPE was not." (PMID 37098488, 2023). "Our results suggest the prognostic value of SNRPD1 but not SNRPE on breast cancer survival, and warrant the use of SNPRD1 in the onco-therapeutic design given its unveiled roles in sensitizing TNBC cells to anthracycline-type of chemotherapies." (PMID 37098488, 2023). "Our results differentiated SNRPD1 from SNRPE at both prognostic and therapeutic levels and preliminarily explained the potential driving mechanisms, with the aim of advancing our therapeutic control of breast cancers via targeting these two genes." (PMID 37098488, 2023). "Basal breast cancer cells are the counterpart of TNBCs at the cell line level, which showed higher SNRPD1 expression than non-basal cells according to the CLM cell line gene expression data (p < 2E−16)." (PMID 33879154, 2021). "Provided with the different roles of SNRPD1 and SNRPE in cell migrative abilities and drug sensitivities that may drive their differential prognostic values on breast cancer survival, we examined their correlated genes to investigate differences on their molecular mechanisms." (PMID 37098488, 2023).
breast carcinoma (continued). "Interestingly, high level of SNRPD1 conveys poor prognostic value on ER-HER2- (mostly TNBC) and ER+HER2- (corresponding to luminal A) tumors, but implicates favorable clinical outcome on ER-HER2+ (HER2+ tumors) breast cancers." (PMID 37098488, 2023). "Triple negative breast cancers (TNBCs) are more malignant and grow faster than the other breast cancer subtypes, which exhibited higher SNRPD1 expression than non-TNBCs in TCGA patient transcriptomic data (p = 8.4E−4) and patient protein data protein_NC (p = 0.0016)." (PMID 33879154, 2021). "Similarly, siRNA-mediated depletion of SNRPE or SNRPD1, components of the core spliceosomal heteroheptameric Sm complex, also led to a marked reduction of cell viability in MDA-MB-468 and SKBR3 breast cancer cells, but not in the non-tumoral MCF-10A cells." (PMID 28198434, 2017).
hepatocellular carcinoma (4 papers, 2022 to 2026). A malignant tumor that arises from hepatocytes. "In this study, we investigated the diagnostic and prognostic significance of SNRPD1 in hepatocellular carcinoma (HCC)." (PMID 34976182, 2022). "The analysis of CCLE exhibited that 29 hepatocellular carcinoma lines have the copy number variation of SNRPD1 mRNA expression." (PMID 34976182, 2022). "It has been reported that SNRPD1 could be an oncogene that affects the development of hepatocellular carcinoma by controlling the mTOR pathway and autophagy." (PMID 38645487, 2024). "Notably, NCBP1, PRPF8, and SNRPD1 were dependent genes in both CRC and hepatocellular carcinoma." (PMID 41195591, 2026).
melanoma (4 papers, 2004 to 2022). A malignant, usually aggressive tumor composed of atypical, neoplastic melanocytes. "Volker and colleagues showed that mutations in SNRPD1 lead to a significant dominance of T cells targeting the mutant epitope in melanoma patients, leading to the development of anti-tumor immunity." (PMID 34976182, 2022). "The mutations SNRPD1 antigenic targets are related to autologous T cell responses in the melanoma model." (PMID 34130650, 2021).
lung adenocarcinoma (3 papers, 2020 to 2024). A carcinoma that arises from the lung and is characterized by the presence of malignant glandular epithelial cells. "Ming Yi and colleagues constructed a gene co-expression network using weighted gene co-expression Network Analysis showed that SNRPD1 was a predictive biomarker of lung adenocarcinoma due to its high expression was associated with poor prognosis." (PMID 34976182, 2022).
breast tumors (2 papers, 2021 to 2023). "SNRPD1 over-expression was used to define subsets of highly aggressive cancers and was proposed as therapeutic targets of multiple cancers such as melanoma, lung and breast tumor cells as a result of induced autophagy." (PMID 33879154, 2021).
ovarian carcinoma (2 papers, 2022 to 2023). A malignant neoplasm originating from the surface ovarian epithelium. "SNRPD1 down-regulation was related to poorer survival in patients with ovarian cancer." (PMID 35356432, 2022).
acute myeloid leukemia (1 paper, 2021). Acute myeloid leukemia (AML) is a group of neoplasms arising from precursor cells committed to the myeloid cell-line differentiation. "SNRPD1 expression is higher in malignant or highly proliferative cells than normal cells in all types of cancers except for LAML (Acute Myeloid Leukemia) according to TCGA mRNA data." (PMID 33879154, 2021).
Cirrhosis (1 paper, 2022). A chronic disorder of the liver in which liver tissue becomes scarred and is partially replaced by regenerative nodules and fibrotic tissue resulting in loss of liver function. "Gender, age, tumor size, ALT, BCLC staging, multinodular, and cirrhosis were not correlated to the SNRPD1 expression." (PMID 34976182, 2022).
neuroblastoma (1 paper, 2012). Neuroblastoma (NB) is the most common solid, extracranial childhood tumor. "We identified six genes (DLGAP5, DSCC1, SMO, SNRPD1, SSBP1, and UBE2C) with a vital role in mitosis and these are promising therapeutic targets for neuroblastoma." (PMID 23251412, 2012).
skin cancer (1 paper, 2022). "The splicing factor SNRPD1 is associated with alternative splicing events in lung, breast, and skin cancer." (PMID 35566209, 2022).
triple-negative breast carcinoma (1 paper, 2021). An invasive breast carcinoma which is negative for expression of estrogen receptor (ER), progesterone receptor (PR), and human epidermal growth factor receptor 2 (HER2). "Our results also warrant special attention in the combined use of drugs targeting SNRPD1 and anthracycline-like chemotherapies in the treatment of triple negative breast cancers, which needs further in vivo validation." (PMID 33879154, 2021). "We also found that triple negative breast cancer cells with reduced SNRPD1 expression lost certain sensitivity to doxorubicin whereas luminal cancer cells did not." (PMID 33879154, 2021). "ROC curves showed the performances of SNRPD1 and KI67 in prognosing triple negative breast cancers (AUC = 0.82 for SNRPD1, AUC = 0.8 for KI67)." (PMID 33879154, 2021). "By applying doxorubicin to SNRPD1-silenced cells, we observed significantly right-ward shifted IC50 in triple negative breast cancer cells MDAMB231 and HCC1937 but not in luminal cells MCF7 and MDAMB361." (PMID 33879154, 2021).
Wilms’ tumour (1 paper, 2024). "This spliceosomal vulnerability likely extends to other components of the spliceosomal machinery such as HNRNPA1, RBM39 and SNRPD3, as well as other cancers such as Wilms’ tumour, where our transcriptomic analyses revealed MYCN regulation of spliceosome regulators including SNRPD1 and WDR77." (PMID 39313128, 2024).
cancer (18 papers, 2012 to 2025). A tumor composed of atypical neoplastic, often pleomorphic cells that invade other tissues. "SNRPD1 is a spliceosome-associated protein and has previously been implicated with important roles in cancer development." (PMID 33879154, 2021). "Several upregulated proteins in the reintervention group, including SNRPD1, SRSF10, SWAP-70, and PSMB1, are associated with tumor progression in other cancer types." (PMID 38157275, 2024). "We conducted in silico analysis at gene expression and genetic levels to differentiate the clinical relevance of SNRPD1 and SNRPE, and explored their differential functionalities and molecular mechanistic associations with cancer in vitro." (PMID 37098488, 2023). "Targeting the deregulated spliceosome core machinery in various cancer cell types, via the genetic inhibition of SNRPE, or SNRPD1, triggers MTOR blockade, which is well known to cause autophagy induction." (PMID 35585060, 2022). "Taking the hubs individually, the results showed that expression of two DEGs, upregulated small nuclear ribonucleoprotein Sm D1 (SNRPD1) and downregulated cofilin 2 (CFL2), was associated with pathological T stage (size of the tumor and any spread of cancer into nearby tissue)." (PMID 38001634, 2023). "There are rare studies investigating the role of FLJ21924 (QSER1) and SNRPD1 in cancers." (PMID 32149105, 2020). "However, only a few studies have reported the role of SNRPD1 in human cancers." (PMID 35356432, 2022). "SNRPD1, SNRPD3, and SNRPD2 have been identified as spliceosome-related proteins that have previously been crucial in the genesis of cancer." (PMID 36389112, 2022). "The expression levels of LSM1-7, SNRPD1-3, SNRPB, SNRPF, SNRPG, SNRPE, and SNRPN were compared between cancer and non-cancer liver tissues in HCC patients from the TCGA and ICGC cohorts." (PMID 35281269, 2022). "In the end, we identified six genes (DLGAP5, DSCC1, SSBP1, UBE2C, SNRPD1, and SMO) with a vital role in prevention of cell death in both cell lines and hence six potential drug targets for silencing in cancer therapy." (PMID 23251412, 2012). "Though suppressed expression of either SNRPD1 or SNRPE led to reduced tumor cell proliferation, SNRPD1 promoted tumor cell migration and sensitized tumor cells to chemotherapy, SNRPE suppressed cancer stemness, and both proteins differ in their dynamic regulations on cell cycle progression." (PMID 37098488, 2023). "Furthermore, two genes involved in splicing (SREK1 and SNRPD1) had some of the most differentially spliced A3SS events, consistent with the importance of autoregulated splicing networks in cancer." (PMID 34440489, 2021). "However, this does not imply that patients with high level of SNRPD1 have, in general, better clinical outcome than those with low SNRPD1 expression given the promotive role of SNRPD1 on cancer cell proliferation and migration." (PMID 37098488, 2023). "However, drugs targeting SNRPD1 may not create desirable therapeutic outcome if coupled with anthracycline-like chemotherapies in cancer treatment." (PMID 37098488, 2023).
tumor (12 papers, 2020 to 2024). "For RFS of HCC, TNM staging (P=0.027), Tumor differentiation (P=0.046), Vascular invasion (P=0.002), Tumor encapsulation (P<0.001), and high SNRPD1 expression (P=0.030) were risk factors." (PMID 34976182, 2022). "The median mRNA expression of SNRPD1 distributed in the tumor tissues in the interactive bodymap is higher than normal tissues." (PMID 34976182, 2022). "Both SNRPD1 and EFNA5 are members of the ‘HALLMARK G2M CHECKPOINT’ gene set, so they participate in cell proliferation and tumour progression via cell cycle arrest at the G2/M‐phase." (PMID 32666642, 2020). "Furthermore, the correlations analysis revealed that five ARGs were associated with tumor purity or seven important immune cells, especially HGF, TRIM22, and SNRPD1." (PMID 37014321, 2023). "In addition, SNRPD1 mRNA expression incrementally upregulated with normal, tumor, and metastatic tissues analyzed in the TNMplot database (p=1.28e-49)." (PMID 34976182, 2022). "As a result, the expression of SNRPD1 in tumour tissues was higher than that in normal tissues." (PMID 32666642, 2020). "Interestingly, the prognostic prediction ability of tumour stage decreased in the multivariate Cox regression combined with two single‐gene signatures, which possibly resulted from the correlation between SNRPD1 expression and tumour stage, as revealed by the process of WGCNA." (PMID 32666642, 2020). "The SNRPD1 protein expression level was significantly correlated to Age (P=0.049), TNM staging (P=0.010), Serum AFP level (P=0.001), Tumor differentiation (P=0.002), Vascular invasion (P=0.006), Recurrence (P=0.036), and Survival (P=0.025)." (PMID 34976182, 2022). "The results showed that the expression of SNRPD1 in HCC tissues was significantly higher than normal liver tissues, and incrementally upregulated with increasing tumor stages." (PMID 34976182, 2022). "The analysis of clinicopathologic characteristics in 154 HCC patients revealed that high SNRPD1 protein expression was significantly correlated to TNM staging, serum AFP level, tumor differentiation, vascular invasion, recurrence, and survival." (PMID 34976182, 2022). "In contrast, SNRPD1 transcripts that use the distal 3′ss have a PTC, again leading to an unstable transcript or protein and thus increased SNRPD1 activity in the tumor would be predicted." (PMID 34440489, 2021).
SNRPD1 also shares sentences with these, for which no sentence is quoted: lung carcinoma (3 papers); systemic lupus erythematosus (3); pulmonary arterial hypertension (2); rheumatic disease (2); alopecia (1); Arthritis (1); autoimmune disease (1); dermatomyositis (1); hematologic disorder (1); infectious mononucleosis (1); Infertility (1); Oral ulcer (1); pulmonary hypertension (1); renal disorder (1); retinoblastoma (1); SARS-CoV Infections (1); scleroderma (1); systemic sclerosis (1).